HNRNPA1 (heterogeneous nuclear ribonucleoprotein A1)
Diseases named in the same sentence as HNRNPA1 in open-access papers (continued):
Sharing a sentence is not in itself a finding about the gene and the disease.
neurodegenerative disease (26 papers, 2014 to 2025). A disorder of the central nervous system characterized by gradual and progressive loss of neural tissue and neurologic function. "These mutations expand the genetic and clinical spectrum of hnRNPA1-associated neurodegenerative diseases by demonstrating their involvement in complex IPN, atypical ALS, and myopathy." (PMID 34291734, 2021). "Similar mutations in the PY-NLS of hnRNPA1 and hnRNPA2 also cause degenerative disease." (PMID 36529289, 2023). "Several RBPs with PrLDs, including hnRNPA1, are implicated in neurodegenerative diseases." (PMID 34291734, 2021). "In addition, several of the identified proteins had previously been linked to neurodegenerative diseases like hnRNPA1, hnRNPA2B1, Matrin3 and FMRP." (PMID 27164932, 2016). "HnRNPA1 has been shown to play a role in concentration-dependent stress granule formation in other neurodegenerative diseases including ALS." (PMID 35259089, 2022). "Continuous evidence shows that hnRNPA1 plays an important role in the pathogenesis of neurodegenerative diseases, including familial ALS, MS, AD and stroke." (PMID 35656110, 2022). "Mutations in RBPs that affect SG biology, including FUS, TDP-43, hnRNPA1, hnRNPA2B1, and TIA1, underlie ALS, IBM, and other neurodegenerative diseases." (PMID 34291734, 2021). "TDP-43, FUS, heterogeneous nuclear ribonucleoprotein A1 (hnRNPA1), and hnRNPA2 are nuclear RBPs with PrLDs that are incorrectly sent to cytoplasmic inclusions in neurodegenerative diseases." (PMID 32269505, 2020). "This could potentially guide therapeutic solutions for neurodegenerative diseases, which typically involve the liquid–solid transition of relevant biomolecular condensates formed by various proteins and nucleic acids, such as hnRNPA1, TDP-43 and FUS19,57–59." (PMID 40481268, 2025). "Accordingly, it is speculated that celastrol may carry therapeutic potential for multiple neurodegenerative diseases by binding to hnRNPA1." (PMID 35656110, 2022). "NIR cargos, such as FUS, TDP-43, and hnRNPA1, which are IDR-containing RBPs, can undergo liquid–liquid phase separation and are involved in different neurodegenerative diseases." (PMID 36101390, 2022). "This type of two-stage nucleation process could be a general pathway for neurodegenerative disease-related phase-separating proteins, as seen in other systems such as FUS, TDP-43, α-synuclein, hnRNPA1, and Tau." (PMID 41409210, 2025). "In recent years, several proteins involved in neurodegenerative diseases, such as Tau, TDP43, FUS, huntingtin, and hnRNPA1, have been reported to form cytosolic condensates, and efforts have been made to describe the physiological and pathological consequences of this phenomenon." (PMID 37585526, 2023). "In addition, HNRNPA1 and HNRNPA2 play an important role in RNA metabolism, which is consistently dysregulated in neurodegenerative diseases." (PMID 33907500, 2021). "HTT, neurofilament heavy chain (NF‐H), Tau (MAPT), FUS, TDP‐43, HNRNPA1, HNRNPD, RPL7 and actin (ACTB, found aggregated in Hirano bodies in several neurodegenerative diseases; Hirano, 1994), were selectively aggregated upon RNase A/T1 treatment of human neuronal lysates." (PMID 32945072, 2020). "We also present the complete list of human proteins with PrLDs and discuss the prevalence of the PrLD in nucleic-acid binding proteins that are often connected to neurodegenerative disease, including: ataxin 1, ataxin 2, FUS, TDP-43, TAF15, EWSR1, hnRNPA1, and hnRNPA2." (PMID 26996412, 2016).
infection (16 papers, 2013 to 2025). The state of being infected such as from the introduction of a foreign agent such as serum, vaccine, antigenic substance or organism. "In the transcriptome results of this study, the encoding genes of BST2, STAT1, and hnRNPA1 were only upregulated in the PEDV 85-7C40 infection process." (PMID 35762780, 2022). "qRT‐PCR and western blotting showed that Hnrnpa1 expression increased in adult mouse MI model hearts after AAV9‐cTnT‐Hnrnpa1 infection." (PMID 39559922, 2025). "This preliminary screening identified hnRNPA1 as a putative interacting partner of NP, 8 h post-infection (p.i)." (PMID 35215793, 2022). "For this, hnRNPA1 expression was transiently upregulated by transfection with human hnRNPA1 cloned in a mammalian expression vector; pcDNA3.1-hnRNPA1, followed by infection with PR8 virus (MOI = 1)." (PMID 35215793, 2022). "Western blot also confirmed that hnRNPA1 expression was successfully induced in VSMCs by Lenti-hnRNPA1 lentiviral infection (Figure VIIIB in the online-only Data Supplement)." (PMID 28912364, 2017). "Interestingly, previous studies have shown that HIV-1 enhances the expression and cytoplasmic relocalization of hnRNPA1 during the late-phase of infection, in order to facilitate adequate viral protein expression before budding." (PMID 34835333, 2021). "Additionally, arginine methylation of hnRNPA1/B2 triggers its export to the cytoplasm where it activates TBK1/IRF3 signaling following infection with a DNA virus." (PMID 34305890, 2021). "Here, we found that infection with SVV induced the redistribution of hnRNPA1 to the cytoplasm." (PMID 34923914, 2021). "Indeed, direct infection of the injured vessels with Lenti-hnRNPA1 significantly increased the expression levels of hnRNPA1 (Figure XA in the online-only Data Supplement) and miR-124 in the injured arteries compared with the control injured vessels." (PMID 28912364, 2017). "One intriguing possibility is through the TRAF6-mediated K-63 ubiquitination and nuclear localization of hnRNPA1 during innate immune activation; if the activity of TRAF6 is inhibited during infection hnRNPA1 activity could drop, leaving TRA2-β pre-mRNA vulnerable to inclusion of the poison exon." (PMID 35127560, 2021). "According to our analysis above, the difference between YN13 and YN144 in replication ability might be due to the difference between the two PEDV-infection groups in alterations of eIF4G1, hnRNPA1, HSP90B1, HSP90AB1, HSPA8, DNAJA1, and DNAJC10 in jejunums of pigs." (PMID 27916855, 2016). "Hnrnpa1 mRNA and protein expression increased significantly at 14 days after AAV9 infection and the AAV9 delivery system sustained Hnrnpa1 overexpression for at least 10 weeks." (PMID 39559922, 2025). "The RNA-binding activity of several proteins increased throughout the infection, such as DDX1, DDX3X, DDX5, and HNRNPA1, indicating that SARS-CoV-2 requires these proteins in the replication and transcription processes." (PMID 37314180, 2023). "Briefly, total RNA isolated from A549 cells treated with either hnRNPA1 specific siRNA or NTC siRNA, followed by infection with PR8 virus (MOI = 1) and subjected to qRT-PCR analysis." (PMID 35215793, 2022). "The subcellular localization of hnRNPA1 was detected, and the results indicated that hnRNPA1 mainly located in nucleus at 0, 3, and 6 h, but partially shuttled from nucleus to cytoplasm at 12 and 24 h post of SHVV infection." (PMID 37005771, 2023). "Based on the preceding findings, we may deduce that hnRNPA1-NP co-localizes in NP transfected and IAV infected cells at early and late stages of infection, further supporting our previous observation." (PMID 35215793, 2022). "Infection of SVV has been shown to induce a variety of cellular factors and their activations are essential for viral replication, but whether heterogeneous nuclear ribonucleoprotein A1 (hnRNP A1) involved in SVV replication is unknown." (PMID 34923914, 2021).
infection (continued). "Ten to 20 μL of DMEM containing 1.0–2.0×106 lentiviral particles (Lenti-hnRNPA1 or Lenti-GFP) was directly infused into the lumen of the injured carotid arteries immediately after injury, followed by a 30-minute incubation period for local VSMC infection." (PMID 28912364, 2017).
myopathy (8 papers, 2020 to 2023). A disease of the muscle in which the muscle fibers do not function properly. "Interestingly, these hnRNPA1 variants cause vacuolar rimmed myopathy, histologically similar to LGMDD3." (PMID 36646699, 2023). "Here, we characterize 4 potentially novel HNRNPA1 mutations (yielding 3 protein variants: *321Eext*6, *321Qext*6, and G304Nfs*3) and 2 known HNRNPA1 mutations (P288A and D262V), previously connected to ALS and MSP, in a broad spectrum of patients with hereditary motor neuropathy, ALS, and myopathy." (PMID 34291734, 2021). "Distal myopathy occurred in 10 patients (5 TIA1, 2 SQSTM1 + TIA1, 1 MATR3, 1 HNRNPA1, 1VCP)." (PMID 36861178, 2023).
neurological diseases (4 papers, 2008 to 2023). "This transition could either be due to the entanglement of biopolymers or stronger association of proteins leading to fibril formation as reported for many protein condensates associated with neurological disorders such as FUS, TDP-43, Tau, and hnRNPA1." (PMID 34944414, 2021).
cardiovascular diseases (2 papers, 2017 to 2021). "At least 6 critical genes, namely CTNNB1, HNRNPA1, SRSF4, TRA2A, SFPQ, and RBM5, and two large clusters of biological terms which are associated with the cardiovascular diseases are deregulated in the presence of omeprazole." (PMID 34659661, 2021). "Our data show that hnRNPA1 is a critical regulator of VSMC function and behavior in the context of neointima hyperplasia, and the hnRNPA1/miR-124/IQGAP1 regulatory axis represents a novel therapeutic target for the prevention of cardiovascular diseases." (PMID 28912364, 2017).
brain diseases (1 paper, 2022). "Additional pathways that lead to generation of aggresomes have not been determined for other proteins known to be involved in brain diseases, including hnRNPA1 and FUS." (PMID 35735914, 2022).
connective tissue disease (1 paper, 2020). "Antibodies to HNRNPA1 have been observed in association with connective tissue disease and RA previously." (PMID 32631453, 2020).
HNRNPA1 also shares sentences with these, for which no sentence is quoted: distal myopathy (4 papers); dementia (3); acute myeloid leukemia (2); cognitive decline (2); diabetic kidney disease (2); diffuse large B-cell lymphoma (2); hereditary spastic paraparesis (2); non-small cell lung carcinoma (2); oculopharyngeal muscular dystrophies (2); preeclampsia (2); adenocarcinoma (1); adrenal cortical carcinoma (1); age-related macular degeneration (1); amyotrophic lateral sclerosis type 20 (1); Amyotrophic lateral sclerosis/frontotemporal dementia (1); anemia (1); astrocytic tumor (1); bipolar disorder (1); Burkitt lymphoma (1); Charcot-Marie-Tooth disease (1); cholangiocarcinoma (1); chronic lymphocytic leukemia (1); chronic progressive multiple sclerosis (1); colitis (1); congenital heart defects (1); congenital myasthenic syndrome (1); depression (1); dilated cardiomyopathy (1); distal hereditary motor neuropathy (1); experimental autoimmune encephalomyelitis (1).
A further 28 diseases each share a sentence with HNRNPA1 in 1 paper.